MTNR1B (melatonin receptor 1B)
Description:
High affinity receptor for melatonin. Likely to mediate the reproductive and circadian actions of melatonin. The activity of this receptor is mediated by pertussis toxin sensitive G proteins that inhibit adenylate cyclase activity.
Synonyms: Mel-1B-R; FGQTL2; MT2
Tractability: Small molecule: an approved drug acts on it; a structure with a bound ligand is known; a high-quality ligand is known; it belongs to a druggable protein family. Antibody: its Gene Ontology location is reachable by antibodies, with high confidence; UniProt places it where antibodies can reach, with medium confidence; UniProt predicts a signal peptide or a membrane-spanning region. PROTAC: a small molecule that binds it is known.
Target class: Membrane receptor; Family A G protein-coupled receptor; Monoamine-derivative receptor (family A GPCR); Melatonin receptor; Small molecule receptor (family A GPCR)
Chemical probes: CHEMBL2326199, CHEMBL3580926, CHEMBL491604, LUZINDOLE (high quality), PD080742, PD080797, PD081648, PD084077, PD084079, UCM 454, UCSF4226 (high quality)
Safety:
Unwanted effects reported when the protein is acted on. In parentheses: how it was acted on, where the effect was seen, and who reports it.
abdominal pain (activation, acute dosing; central nervous system; source: Lynch et al. (2017))
decreased anxiety (activation, acute dosing; central nervous system; source: Lynch et al. (2017))
decreased blood pressure (activation, acute dosing; central nervous system; source: Lynch et al. (2017))
decreased memory (inhibition, acute dosing; central nervous system; source: Lynch et al. (2017))
decreased pain (activation, acute dosing; central nervous system; source: Lynch et al. (2017))
decreased sleep (inhibition, acute dosing; central nervous system; source: Lynch et al. (2017))
increased memory (activation, acute dosing; central nervous system; source: Lynch et al. (2017))
increased sleep (activation, acute dosing; central nervous system; source: Lynch et al. (2017))
nightmares (activation, acute dosing; central nervous system; source: Lynch et al. (2017))
Gene: Protein-coding gene on chromosome 11 (92,969,651 to 92,985,066, forward strand). Ensembl gene ENSG00000134640.
Subcellular location: Cell membrane
Pathways (Reactome):
Signal Transduction: Class A/1 (Rhodopsin-like receptors); G alpha (i) signalling events
Gene Ontology:
Molecular function: protein binding; G protein-coupled receptor activity; melatonin receptor activity
Biological process: glucose homeostasis; regulation of insulin secretion; chemical synaptic transmission; G protein-coupled receptor signaling pathway; G protein-coupled receptor signaling pathway, coupled to cyclic nucleotide second messenger; camera-type eye development; negative regulation of cytosolic calcium ion concentration; negative regulation of insulin secretion; negative regulation of neuron apoptotic process; negative regulation of receptor guanylyl cyclase signaling pathway; negative regulation of transmission of nerve impulse; negative regulation of vasoconstriction; positive regulation of circadian rhythm; positive regulation of circadian sleep/wake cycle, non-REM sleep; positive regulation of transmission of nerve impulse; regulation of neuronal action potential
Cellular component: plasma membrane; membrane; synapse
Genetic constraint (gnomAD): Loss-of-function variants: 9 observed, 6.37 expected, observed/expected ratio (o/e) 1.41, 90% interval 0.82 to 1.92. That is too few expected variants to judge how well the gene tolerates losing a copy. Missense variants: 478 observed, 493.51 expected, observed/expected ratio (o/e) 0.97, 90% interval 0.9 to 1.04. Synonymous variants: 226 observed, 214.09 expected, observed/expected ratio (o/e) 1.06, 90% interval 0.95 to 1.18.
Homologues: Orthologues: chimpanzee MTNR1B (99% identical), rabbit MTNR1B (84% identical), guinea pig MTNR1B (80% identical), pig MTNR1B (80% identical), mouse Mtnr1b (79% identical), rat Mtnr1b (79% identical), tropical clawed frog MTNR1B (64% identical), dog MTNR1B (62% identical). Paralogues in human: MTNR1A (56% identical), GPR50 (43% identical), PRLHR (23% identical), NPY2R (22% identical), NPY1R (22% identical), TACR1 (22% identical), GPR83 (21% identical), NPY4R (21% identical), NPY4R2 (21% identical), TACR2 (21% identical), TACR3 (21% identical), MCHR1 (20% identical), and 21 more.
Diseases named in the same sentence as MTNR1B in open-access papers:
MTNR1B is named in the same sentence as 82 diseases in open-access papers, as found by Europe PMC text mining. Sharing a sentence is not in itself a finding about the gene and the disease. The quoted sentences say what the papers report.
type 2 diabetes (79 papers, 2008 to 2026). "Related studies have shown that the G risk allele in MTNR1B rs10830963 is associated with higher MTNR1B expression, leading to enhanced inhibition of insulin secretion by melatonin, impaired insulin secretion, and increased risk of type II diabetes." (PMID 41002997, 2025). "Although the MTNR1B single nucleotide polymorphism rs10830963 has been strongly associated with the onset of type 2 diabetes (T2D), its association with the progression and prognosis of T2D has been understudied." (PMID 40869173, 2025). "We conducted a cross-sectional study, performing MTNR1B variant burden testing of glycaemic phenotypes (N=248,454, without diabetes), other cardiometabolic phenotypes (N=330,453) and type 2 diabetes prevalence (case–control study; N=263,739) in the UK Biobank." (PMID 40064676, 2025). "A key finding was the strong association of the MTNR1B gene with metabolic phenotypes, including type 2 diabetes and obesity." (PMID 40697662, 2025). "We have recently reported the association of variants in MTNR1A and MTNR1B genes with familial type 2 diabetes." (PMID 38217063, 2024). "MTNR1B is a protein coding gene that has been associated with type 2 diabetes in several studies and glycemic traits." (PMID 38938516, 2024). "We have recently reported the linkage and linkage plus association of variants in MTNR1A with familial type 2 diabetes and in MTNR1B with familial type 2 diabetes and type 2 diabetes-depression comorbidity." (PMID 38217063, 2024). "The purpose of this study is to investigate the association of rotating night shift work, CLOCK, MTNR1A, MTNR1B genes polymorphisms and their interactions with type 2 diabetes among steelworkers." (PMID 37138267, 2023). "Numerous studies confirmed the association between MTNR1B gene polymorphisms and the risk of type 2 diabetes." (PMID 37511203, 2023). "The association between rotating night shift work and risk of type 2 diabetes appeared to be modified by MTNR1B gene rs1387153 locus (RERI = 0.98, (95% CI, 0.40–1.55); AP = 0.60, (95% CI, 0.07–1.12))." (PMID 37138267, 2023). "Genetic variations of the melatonin receptor 1B gene (MTNR1B) play an important role in the development of type 2 diabetes, a risk factor for cardiovascular diseases." (PMID 37511203, 2023). "Rotating night shift work and rs1387153 variants in MTNR1B were associated with an increased risk of type 2 diabetes even after multivariate adjustment." (PMID 37138267, 2023). "Rotating night shift work and rs1387153 variants in MTNR1B were associated with an increased risk of type 2 diabetes among steelworkers." (PMID 37138267, 2023). "In contrast, this study suggested that the MTNR1B gene rs1387153 locus was associated with the increased risk of type 2 diabetes, which was supported by some studies." (PMID 37138267, 2023). "MTNR1B is known for its role as coding for the melatonin receptor, but is also associated with other diseases such as type 2 diabetes." (PMID 35884569, 2022). "On the other hand, carriers of rare loss‐of‐function variants in the MTNR1B and individuals with low nightly melatonin secretion have increased risk of type 2 diabetes." (PMID 35619221, 2022). "We used the ‘insulin secretion’ pPS of variants in eight genes associated with type 2 diabetes risk due to poor beta cell function: MTNR1B, HNF1A, GCK, TCF7L2, TMEM258, ADCY5, SLC3OA8 and ABO." (PMID 35247066, 2022). "The purpose of this study was to analyze the effect of MTNR1B rs10830963 gene variant on the efficacy of nateglinide in treating the newly diagnosed type 2 diabetes patients." (PMID 34118937, 2021). "In summary, the results of this study suggest that the MTNR1B rs10830963 gene variant is associated with the efficacy of nateglinide in the treatment of type 2 diabetes, and also has a certain role in promoting clinical individualized drug delivery." (PMID 34118937, 2021).
type 2 diabetes (continued). "In a model adjusted for sex, age (as continuous), type-2 diabetes, and obesity, a statistically significant interaction was obtained between age and the MTNR1B-rs10830963 polymorphism (p = 0.001)." (PMID 33138317, 2020). "(a) Odds ratios and 95% CIs for the association between MTNR1B rs10830963 genotype and type 2 diabetes, separated by chronotype." (PMID 31623012, 2020). "Given that the prevalence of type-2 diabetes in this replication cohort 1 is high (46.4%) compared with the discovery cohort, we analyzed the association between the MTNR1B-rs10830963 and type-2 diabetes prevalence." (PMID 33138317, 2020). "A common variant in MTNR1B—MTNR1B rs10830963 is associated with increased risk of type 2 diabetes, increased fasting plasma glucose levels and impaired early insulin secretion." (PMID 31379733, 2019). "Genotypes and frequencies of MTNR1B polymorphisms in patients with type 2 diabetes mellitus (T2DM) (n = 300) and healthy controls (n = 200)." (PMID 31787898, 2019). "The gene that encodes the melatonin receptor 1B (MTNR1B) has been identified as a novel type 2 diabetes (T2D) risk gene." (PMID 31684003, 2019). "MTNR1B, a melatonin receptor gene, is a common variant associated with an increased risk of future type 2 diabetes and impaired early insulin secretion." (PMID 29777116, 2018). "Prior reports confirmed that MTNR1B rs10830963 is a true causal gene variant in type 2 diabetes development which impaired the early-phase insulin response and also increased the odds of GDM development." (PMID 30477160, 2018). "Genetic variants at KCNQ1 rs151290, KLF14 rs972283, GCKR rs780094 and MTNR1B rs10830963 have been associated with type 2 diabetes mellitus (T2DM), but the results are contradictory in Chinese populations." (PMID 26927145, 2016). "Large-scale exon resequencing around an MTNR1B SNP modestly associated with type 2 diabetes (OR between 1.10 and 1.15) identified four rare variants that led to loss of melatonin binding and signalling capacity (OR 5.67, 95% CI 2.17–14.82)." (PMID 25145545, 2014). "Our results demonstrated that the rs10830963 polymorphism of MTNR1B is a risk factor for developing type 2 diabetes." (PMID 23226241, 2012). "We have recently shown that among type 2 diabetes-associated loci, risk alleles at MTNR1B, GCK and SLC30A8 confer a stronger rate of progression from normoglycemia to IFG than from IFG to type 2 diabetes." (PMID 22984506, 2012). "Recent data suggest that melatonin also has a regulatory role, as it has been demonstrated that the presence of one of its gene polymorphisms (MTNR1b) increases the risk of developing type 2 diabetes mellitus." (PMID 22296806, 2012). "After that, another four studies reported that MTNR1B rs10830963 was associated with type 2 diabetes and/or fasting glucose in Han Chinese populations." (PMID 21470412, 2011). "As diabetes is one of the risk equivalents of coronary heart disease (CAD), and the MTNR1B polymorphism is associated with type 2 diabetes and lipid levels in the present study, do they also contribute to the development of CAD?" (PMID 21470412, 2011). "Our study demonstrated that MTNR1B rs3781637 A/G polymorphism is associated with type 2 diabetes, total cholesterol and LDL-C levels in the Han Chinese population." (PMID 21470412, 2011). "In this analysis, the reported type 2 diabetes risk alleles for rs1387153 and rs10830963 in the MTNR1B locus had significant association with reduced beta-cell function or increased FPG." (PMID 22046406, 2011). "We investigated the association of polymorphisms in the MTNR1B gene with type 2 diabetes by employing a case-control study design (1118 cases and 1161 controls)." (PMID 21470412, 2011). "Here we reported that a common genetic variant rs3781637 in MTNR1B was associated with type 2 diabetes in a Han Chinese population." (PMID 21470412, 2011).
type 2 diabetes (continued). "In this analysis, we also found that HMGA2 locus was significantly associated with increased FPG in these samples, suggesting that SNPs in the MTNR1B or the HMGA2 loci confer susceptibility to type 2 diabetes in Japanese populations." (PMID 22046406, 2011). "Several studies investigated the associations of MTNR1B rs10830963 with type 2 diabetes and fasting glucose among Han Chinese populations." (PMID 21470412, 2011). "The rs3781637 A/G polymorphism of the MTNR1B gene is associated with type 2 diabetes, plasma, total cholesterol and LDL-C levels in the Han Chinese population." (PMID 21470412, 2011). "Several replication studies in European, Indian, Sri Lankan and Japanese populations confirmed that MTNR1B rs10830963 contributed to raised fasting glucose level and increased risk of type 2 diabetes." (PMID 21470412, 2011). "Several studies have shown that common variants in the MTNR1B gene were associated with fasting glucose level and type 2 diabetes." (PMID 21470412, 2011). "Association between GCK, GCKR, G6PC2 and MTNR1B variants and type 2 diabetes in the Chinese population." (PMID 20668700, 2010). "In the present study, we assessed the impact of common genetic variation within the novel type 2 diabetes risk gene MTNR1B on the pathogenesis of obesity and the prediabetic phenotypes insulin resistance and β-cell dysfunction." (PMID 19088850, 2008). "Very recently, a novel type 2 diabetes risk gene, i.e., MTNR1B, was identified and reported to affect fasting glycemia." (PMID 19088850, 2008). "Very recently, an additional type 2 diabetes risk gene, i.e., MTNR1B, was identified and reported to affect fasting plasma glucose concentrations." (PMID 19088850, 2008). "Similarly, a study conducted in China on more than 30 000 pregnant women identified four loci associated with GDM, among which MTNR1B exhibited the strongest association with GDM while having a more modest effect on type 2 diabetes risk." (PMID 41338933, 2025). "Thus, we aimed to gain further insights into the impact of MTNR1B coding variants on type 2 diabetes prevalence and related phenotypes." (PMID 40064676, 2025). "MTNR1B codes for a transmembrane receptor of melatonin, and its mutations have been associated with wide‐ranging health effects including type 2 diabetes and sleep and neuropsychiatric disorders, conditions that are also more frequent among offspring of older mothers." (PMID 38808605, 2024). "Recently, MTNR1B has increased the risk of obesity and type 2 diabetes." (PMID 36997916, 2023). "The present analysis showed that rotating night shift work and MTNR1B gene rs1387153 locus were associated with increased risk of type 2 diabetes, and the association between rotating night shift work and risk of type 2 diabetes appeared to be modified by MTNR1B gene rs1387153 locus." (PMID 37138267, 2023). "The findings of the study provide evidence that encoding the MTNR1B gene may play a role in type 2 diabetes etiology, as the MTNR1B gene was associated with type 2 diabetes risk in this data." (PMID 37138267, 2023). "MTNR1B mutations have been associated with increased blood glucose and risk of type 2 diabetes." (PMID 36658621, 2023). "Moreover, it was shown that the rs10830963 C/G gene melatonin receptor 1B (MTNR1B) polymorphism was associated with an increased risk of type 2 diabetes (T2DM)." (PMID 37958842, 2023). "In addition, there is little epidemiological evidence about the interaction between CLOCK, MTNR1A, MTNR1B genes polymorphisms and shift work on type 2 diabetes." (PMID 37138267, 2023). "Type 2 diabetes is associated with both dietary iron intake and single-nucleotide polymorphism (SNP) of intronic rs10830963 in melatonin receptor 1B (MTNR1B); however, it is unclear whether they interact." (PMID 37111205, 2023).